INS (insulin)
Diseases named in the same sentence as INS in open-access papers (continued):
Sharing a sentence is not in itself a finding about the gene and the disease.
diabetes (continued). "Insulin as a monotherapy for diabetes mellitus was received by 22,004 (0.8%) persons, and oral anti-diabetic agents as monotherapy were received by 45,664 (1.6%) persons." (PMID 23186328, 2012). "It was previously associated to insulin sensitivity, glucose uptake, and insulin secretion by beta cells and, in this study, data suggest that the polymorphism may increase susceptibility to chronic metabolic conditions such as diabetes in the Brazilian population." (PMID 23243416, 2012). "In an animal model of diabetes, Pg resulted in lower serum C-peptides, a pro-insulin metabolite marker for endogenously secreted insulin, by 23 percent compared to baseline levels in diabetic patients." (PMID 24250463, 2012). "The mean age of respondents was 67.0 years with 11.9% reporting using insulin, 73.9% using tablets, 59.8% diet and 29.6% physical activity to help control their diabetes." (PMID 22859997, 2012). "Pancreatic beta cells compensate for insulin resistance by hypersecretion of insulin; however, at some point, pancreatic beta cells fail to secrete sufficient insulin, resulting in diabetes." (PMID 22474424, 2012). "It is, therefore, of the uttermost urgency to devise novel approaches to counteract diabetes-related muscle weakness and abnormal hormone signaling in of the most crucial insulin-dependent organs for glucose disposal." (PMID 22523676, 2012). "As detailed in the Introduction, the artificial pancreas idea can be traced back to the early 70s, when external BG regulation in people with diabetes was achieved by i.v. glucose measurement and i.v. infusion of glucose and insulin." (PMID 24278682, 2012). "It is well known that the release of glucagon by the pancreas is inhibited by both insulin and somatostatin; and in diabetes, defects in the release of these islet paracrine hormones contribute to the perturbation of glucagon release from α-cells." (PMID 22969729, 2012). "Diabetes mellitus is a metabolic disorder characterized by hyperglycemia (high blood sugar) resulting from defects in the production or response to insulin." (PMID 23612026, 2012). "Approximately 11% of participants reported they had been diagnosed with diabetes, compared with 16% who were diagnosed by laboratory testing and 19% who were diagnosed by laboratory testing or current use of insulin or an oral hypoglycemic medication." (PMID 22172192, 2012). "This decrease in cardiac SUR-2A and Kir6.2 mRNA levels of rats with diabetes for 8 weeks was reversed after 4 days of insulin treatment to approximately the same level which existed in control rats." (PMID 22257425, 2012). "These animals developed severe diabetes, due to the inability of β-cells to expand in response to a state of resistance to insulin." (PMID 24893199, 2012). "Since the introduction of sulfonylureas, multiple medications have been introduced for the treatment of diabetes mellitus type 2, substituting or supplementing insulin." (PMID 23882374, 2012). "It decreases blood glucose levels in animal models of type 1 or type 2 diabetes mellitus, reduces insulin secretion in animals with hyperinsulinemia, inhibits cytokine actions and attenuates oxidative damage in pancreatic tissue." (PMID 23226280, 2012). "In some studies, pregnancy complications such as diabetes controlled with insulin, abortion and IUGR in pregnant women of PCOS treated with metformin had a significant reduction in comparison with control group." (PMID 25243003, 2012). "Hypoglycemia is a common complication of insulin treatment in type 1 diabetes mellitus and can occur in any patient with diabetes when glucose consumption exceeds supply." (PMID 22716962, 2012). "For example, during the diabetes onset epigenetic changes act on insulin and insulin metabolism regulating the gene coding." (PMID 22524430, 2012).
diabetes (continued). "Our survey results of 134 Japanese physicians show that, in the management of diabetes, non-diabetes specialists have more concerns about insulin initiation than specialists, and that most of the concerns among non-specialists are related to practical burdens." (PMID 22719830, 2012). "Increased insulin release in response to glucose is central to energy homeostasis, and is impaired in diabetes." (PMID 24970137, 2012). "STZ administration to mature rats induces severe and permanent diabetes, with a decrease in insulin levels, to produce a cytotoxic model of diabetes very similar to type I DM." (PMID 22844268, 2012). "In conditions of insulin resistance, such as central obesity, type 2 diabetes mellitus with obesity, and essential arterial hypertension, a deep reduction of platelet sensitivity to the antiaggregating effects of insulin has been reported." (PMID 24278711, 2012). "Insulin allergy to human insulin preparations during the treatment of diabetes is suggested to occur at rates ranging from <1.0% to 2.4%." (PMID 22937994, 2012). "Hypoglycemia is one of the most common acute complications of insulin therapy in children and adolescents with diabetes." (PMID 23497433, 2012). "The UK Prospective Diabetes Study showed that although monotherapy with metformin and also sulfonylureas or insulin can achieve good glycemic control initially, sustained control with these agents fails in 50% of patients after three years." (PMID 22611498, 2012). "Diabetes mellitus is a metabolic disease characterized by hyperglycemia resulting from defects in insulin action, insulin secretion or both." (PMID 22609782, 2012). "Animal models of diabetes exhibit impaired learning and memory, effectively prevented by administration of insulin." (PMID 22383997, 2012). "Diabetes can be stratified into two groups with type 1 diabetes being insulin dependent and type II insulin independent." (PMID 22611498, 2012). "Our study not only confirms what has been reported in previous studies, but provides a deeper insight into the perspectives of insulin treated patients with diabetes." (PMID 22397638, 2012). "PPARγ agonists such as thiazolidinediones (TZDs) have been used clinically as insulin sensitizers for treatment of diabetes, but with side effects including body weight gain and cardiac problems." (PMID 22859932, 2012). "The iminosugar N-(5′-adamantane-1′-yl-methoxy)-pentyl-1-deoxynoijirimycin (AMP-DNM), an inhibitor of glycosphingolipid (GSL) biosynthesis is known to ameliorate diabetes, insulin sensitivity and to prevent liver steatosis in ob/ob mice." (PMID 23056165, 2012). "Lipid peroxide mediated tissue damage has been demonstrated in insulin dependent and non-insulin-dependent diabetes mellitus." (PMID 22734822, 2012). "Newer medications complement and enhance insulin action tailored toward different mechanisms in the pathophysiology of diabetes mellitus." (PMID 23882369, 2012). "Characteristics associated with greater GHb reduction include male sex, higher education and longer duration of diabetes, insulin treatment regimen, smoker, higher FPG at the baseline and older at registration and diagnosis." (PMID 23119180, 2012). "The discovery of insulin in 1922 marked a major breakthrough in medicine and therapy in patients with diabetes." (PMID 23882369, 2012). "Duration of diabetes was longer for patients prescribed one or more diabetes medicines (oral hypoglycaemic agents (OHAs), insulin, lipid lowering agent, and antihypertensive agent) than patients not prescribed one of these medicines." (PMID 22518307, 2012). "AMPK is insulin sensitive, and in diabetes a reduction in AMPK activity leads to a decrease in muscle glucose uptake thus shifting fuel from glucose to fat for cardiac myocyte function." (PMID 22007304, 2012). "4-week HFD feeding resulted in high plasma levels of glucose and insulin, suggesting that the mice showed indications of diabetes." (PMID 22347463, 2012).
diabetes (continued). "The secretion of insulin by pancreatic islet β-cells plays a pivotal role in glucose homeostasis and diabetes." (PMID 24970137, 2012). "It is interesting to note that alterations in these signals were reported in defective insulin secretion from β cells, insulin sensitization in peripheral tissues, and complication-related cell injury and tissue damage in diabetes." (PMID 22611498, 2012). "Different reports have shown that the islets appear to be preferentially affected in diabetes by destruction of insulin-secreting β-cells." (PMID 23190471, 2012). "Type 1 diabetes mellitus (T1DM) accounts for 5–10% of those with diabetes and is characterised by an absolute deficiency of insulin caused by immunologically mediated damage to the beta-cells in the pancreas." (PMID 23237320, 2012). "Twenty-four percent of a cohort of 100 patients had diabetes, with a quarter of those needing insulin therapy, in addition to other endocrinopathies such as hypothyroidism and hypogonadism." (PMID 22284844, 2012). "Changes in NMDA receptor function and expression have been described in animal models of diabetes and as a direct response to application of insulin." (PMID 22383997, 2012). "Endothelial cell dysfunction typically occurs when these protective stimuli are diminished, such as at sites of turbulent blood flow (decreased shear stress), in diabetes (decreased insulin signaling), and in obesity (decreased adiponectin)." (PMID 22489274, 2012). "Individuals in the diabetes group were older and more likely to have higher mean BP, heart rate (HR), BMI, TC, TG, glucose, insulin, and HOMA-IR, and lower HDL-C, FEV1 (L), and FVC (L) values compared with those in the non-diabetes group." (PMID 22524685, 2012). "Diabetes status and insulin use in patients with type 2 diabetes before 2005 were the main exposures of interest and the first event of HP eradication in 2005 was the main outcome evaluated." (PMID 22571603, 2012). "Non-profit, non-government health organisations play an important role in providing counselling services and support in terms of health education, peer group programmes and financial assistance to patients with diabetes who need insulin initiation." (PMID 22545648, 2012). "Monogenic diabetes forms can be divided into 2 large groups, resulting from impaired insulin secretion or from an abnormal response to insulin." (PMID 22996131, 2012). "Since, ER stress also promotes insulin resistance, generating a vicious cycle that leads to plaque instability, so its suppression would be helpful in management of diabetes and vulnerable plaque management." (PMID 22891067, 2012). "Overall, patients initiating exenatide b.i.d. reported a significantly shorter mean duration of diagnosed diabetes than those initiating insulin (8 ± 6 vs. 10 ± 7 years, respectively; P < 0.0001)." (PMID 22714818, 2012). "In accordance with previous studies we found a positive correlation between insulin sensitivity and VO2peak in heart failure patients, which remained unaffected when leaving out patients with diabetes." (PMID 22889317, 2012). "In the last three decades, brain insulin signaling has faced a novel and increased interest in neuroscience research, either in its signaling pathways and/or as a promising therapy against diabetes and age-related neurodegenerative disorders (e.g., AD)." (PMID 22500228, 2012). "The type of malignancy which seems to be more closely associated with insulin therapy in patients with type 2 diabetes is pancreatic cancer; the reported incidence in insulin-treated individuals is two- to five-fold higher than in other patients with diabetes." (PMID 23209929, 2012). "Pancreas stem cells are a potential source of insulin-producing β cells for the therapy of diabetes." (PMID 23152835, 2012). "Lastly, because PPARγ function is important in regulating insulin sensitivity and polymorphisms in PON2 have been associated with diabetes, we evaluated associations with fasting blood glucose levels." (PMID 22860094, 2012).
diabetes (continued). "Genetic analysis using the BB rat revealed that at least three genes are involved in the development of insulin-dependent diabetes mellitus: Lyp (Iddm1), which controls T cell lymphopenia, an MHC-linked gene (Iddm2), and the third gene (Iddm3)." (PMID 23118743, 2012). "Several studies have shown a link between disturbances of circadian rhythm and metabolic diseases, including diabetes, as well as a clear relationship between insulin and melatonin." (PMID 23226241, 2012). "Insulin-degrading enzyme (IDE) is an allosteric Zn+2 metalloprotease involved in the degradation of many peptides including amyloid-β, and insulin that play key roles in Alzheimer's disease (AD) and type 2 diabetes mellitus (T2DM), respectively." (PMID 22355395, 2012). "These evidences suggest that ER stress is a major player in the establishment of important human pathologies such as diabetes, characterized by high blood glucose levels, contributing to pancreatic ß-cell death and insulin resistance." (PMID 22384074, 2012). "One aspect of the maternal findings of the present analysis requires further comment; women using insulin glargine had longer duration of diabetes than those using NPH insulin." (PMID 22685467, 2012). "Diabetes mellitus is characterised by chronic hyperglycemia resulting from impaired insulin action/secretion and is classified into two major categories, type 1 and type 2." (PMID 23243452, 2012). "In diabetes, however, while insulin secretion or action is insufficient, the production and secretion of glucagon are excessive, contributing to the development of diabetic hyperglycemia." (PMID 23316165, 2012). "Diabetes mellitus is a group of metabolic disorders resulting from defects in insulin secretion or reduced sensitivity of the tissues to insulin action or both." (PMID 24250443, 2012). "Firstly, the type of insulin present in the milk of mothers with type 1 diabetes mellitus was assessed." (PMID 22500167, 2012). "Some HCPs felt that the media played an important role in educating the public about diabetes and the benefits of insulin." (PMID 22545648, 2012). "The lack of integration and collaboration of the dual-sector health system is a major barrier for insulin initiation in patients with diabetes." (PMID 22545648, 2012). "Elevated fasting insulin levels have been shown to contribute to the progress to diabetes and CVD among individuals with normoglycemia." (PMID 22731255, 2012). "Transgenic mice overexpressing the active form of Akt1 under the rat insulin promoter had increased numbers of β cells and high plasma insulin levels, leading to improved glucose tolerance and resistance to diabetes." (PMID 22384192, 2012). "Although privately-sponsored diabetes nurse educators were available to help educate patients on starting insulin in private clinics, there were very few of them." (PMID 22469132, 2012). "The Diabetes Mellitus, Insulin Glucose in Acute Myocardial Infarction (DIGAMI) trial involved 620 patients with an acute MI." (PMID 23209941, 2012). "DISABKIDS results were related to age, gender, duration of diabetes, mode of insulin delivery and metabolic control." (PMID 22300248, 2012). "Respondents found the question with regard to changes in diabetes-specific therapy (medication, insulin) in the previous 6 months unclear or difficult." (PMID 22950744, 2012). "Our study was designed to evaluate the long-term diabetic control of children with type 1 diabetes mellitus (T1DM) who had transitioned to an insulin pump." (PMID 22985612, 2012). "Pregnant women aged 18 and over with either diabetes mellitus type 1 or 2 on insulin therapy or with gestational diabetes requiring insulin therapy before 30 weeks of gestation will be asked to participate." (PMID 23270328, 2012).
diabetes (continued). "DPP-4 inhibitors are considered effective for the treatment of type 2 diabetes mellitus in Asian patients, including Japanese patients, who often have insufficient insulin secretion, in contrast to Caucasian patients who usually have insulin resistance." (PMID 22867630, 2012). "First, the 286 internode genes showed significant enrichment of functional categories, like “regulation of beta cell development” (p = 2.1×10−79), “insulin synthesis and secretion” (p = 3.4×10−79) and “diabetes pathways” (p = 1.9×10−35)." (PMID 23236286, 2012). "Diabetes can progressively evolve towards insulin requirement, but inaugural ketoacidosis has also been reported." (PMID 22284844, 2012). "Beyond neonatal diabetes mellitus (NDM), KCNJ11 is also a MODY gene (‘MODY13’), confirming the wide spectrum of diabetes related phenotypes due to mutations in NDM genes (i.e. KCNJ11, ABCC8 and INS)." (PMID 22701567, 2012). "Consumption of the viscous non-fermentable fiber HPMC decreased diabetic wasting, improved glucose control and reduced insulin resistance and fatty liver in a model of obesity with diabetes." (PMID 23146593, 2012). "Thirty-seven carriers (52.1%) had a compromised glucose tolerance, for which ten were treated with tablets (non insulin depending diabetes mellitus) and 20 required insulin treatment (insulin depending diabetes mellitus)." (PMID 22403016, 2012). "Increased physical activity, which is a requisite therapy for diabetics, can promote phosphorylation of mTORC1 components Raptor, p70S6K, and 4EBP1 to assist with insulin signaling." (PMID 22545721, 2012). "In order to prevent or delay the progression of diabetes, insulin should be sufficiently secreted to compensate for insulin resistance in peripheral tissues." (PMID 22645628, 2012). "The glucose lowering drug metformin reduces plasma FFA concentrations in patients with type 2 diabetes mellitus and improves insulin sensitivity." (PMID 23094143, 2012). "Insulin concentration varies in different types of diabetes (depending on the type and progress of metabolic disorder) and is often massively modified by antidiabetic treatment." (PMID 22262970, 2012). "Four out of ten participants were male and at baseline the pooled average age was 60 years (SD 9.5), BMI 31.5 (SD 5.6), diabetes duration was 8.1 years (SD 7.0), HbA1c level 8.23% (SD 1.80), and 81.9% used insulin and/or oral glucose lowering agents." (PMID 22824531, 2012). "Insulin analogues were developed to improve treatment of insulin-treated diabetes with respect to glycaemic control and avoidance of hypoglycaemic episodes." (PMID 22727048, 2012). "In 1923, August Krogh, from the University of Copenhagen, met with Banting and Macleod to learn more about insulin because his wife had diabetes mellitus." (PMID 23882369, 2012). "Type 2 diabetes mellitus is characterized by insulin resistance, which results in lower levels of insulin-induced blood glucose uptake into target tissues." (PMID 22470480, 2012). "Diabetes mellitus is a metabolic disorder characterized by chronic hyperglycemia with impaired metabolism of carbohydrate, fat and protein resulting from defects in insulin secretion or insulin action or both." (PMID 22489136, 2012). "Analysis on inpatient insulin treatment for pregnant women with diabetes has shown that this therapeutic strategy is effective." (PMID 22344355, 2012). "Diabetes mellitus, one of the most common metabolic disorders, is a major disorder of insulin regulation." (PMID 22500228, 2012). "The subsequent development of precisely engineered insulin analogs, which are more physiologic, improved diabetes control and reduced or delayed complications." (PMID 23882369, 2012). "All models were adjusted for age, diabetes duration, total daily insulin dose, statin use, BMI, blood pressure, presence of microalbuminuria and/or overt nephropathy, and smoking." (PMID 23270560, 2012).